Y_RNA (Y RNA )
Gene: Miscellaneous RNA gene on chromosome 4 (88,330,176 to 88,330,278, reverse strand). Ensembl gene ENSG00000207480.
Homologues: Orthologues: chimpanzee Y_RNA (98% identical), macaque Y_RNA (92% identical). Paralogues in human: Y_RNA (86% identical), Y_RNA (85% identical), Y_RNA (84% identical), Y_RNA (83% identical), RNY3 (83% identical), RNY3P1 (82% identical), Y_RNA (82% identical), Y_RNA (81% identical), RNY3P11 (80% identical), Y_RNA (80% identical), RNY3P5 (79% identical), RNY3P7 (79% identical), and 95 more.